TLR8 (toll like receptor 8)
Diseases named in the same sentence as TLR8 in open-access papers (continued):
Sharing a sentence is not in itself a finding about the gene and the disease.
COVID-19 (continued). "Treatment of these whole blood samples with the small molecule R848, a mimic of TLR7 and TLR8 activation by single strand RNA, increased the percentage of IL-6+ blood monocytes, with significantly higher levels in samples from COVID-19 patients compared to healthy controls." (PMID 32503877, 2020). "While haplotypes GGG and ACA were found for TLR8, with a dominance of haplotype ACA only in the TNFHIFNγN-L group, these results suggest that these genotypes may be associated with high TNF/IFN-γ levels during COVID-19." (PMID 39940907, 2025). "The immunoblotting results revealed that the levels of COVID-19 EV-induced NETs-associated proteins [e.g., myeloperoxidase (MPO), peptidylarginine deiminases 4 (PAD4), and citrullinated histone H3 (citH3)] were inhibited completely in TLR8 knockdown cells, which was consistent with IFA data." (PMID 37904132, 2023). "While SARS-CoV-2 ssRNA can trigger a TLR8-dependent inflammatory response from macrophages in vitro, it was suggested by others that TLR8 is of lower clinical importance in COVID-19, due to its lack of expression on pDCs and that no deleterious TLR8 variants were found in severe patients." (PMID 34858409, 2021). "In COVID-19, the induction of a cytokine storm is mainly regulated by TLR3, TLR4, TLR7, and TLR8 and triggers an excessive inflammatory response, leading to severe disease and death." (PMID 39940907, 2025). "IMQ does not stimulate the innate immune system of people who present these unfunctional TLR7 variants; therefore, young individuals with TLR7 mutants develop severe COVID-19, suggesting that TLR7 and TLR8 are important in SARS-CoV-2 protection." (PMID 39062904, 2024). "In COVID-19, TLRs, especially TLR7 and TLR8, which bind to single-stranded RNA, are enriched in lung tissues and play critical roles in different stages of the immune response." (PMID 38932146, 2024). "Given that mature neutrophils express all TLRs except TLR3, we analyzed the expressions of TLR7, TLR8 and TLR9 in normal human neutrophils after being treated with EVs from COVID-19 patients (n = 6) and HC subjects (n = 6), respectively." (PMID 37904132, 2023). "Another study reported decreased functioning of DCs from COVID-19 patients towards TLR triggers during acute SARS-CoV-2 infection as DC activation upon TLR3, TLR4, TLR7 and TLR8 triggering was suppressed." (PMID 37844099, 2023). "The COVID-19 patient–derived EV-induced NETs formation was reduced in TLR7- and TLR8- knockdown cells, respectively." (PMID 37904132, 2023). "Having observed differential expression of type III and II IFNs in the lower respiratory tracts of COVID-19 patients, we evaluated TLR expression in BALs; in particular, deceased patients showed lower expression levels of TLR7 and TLR8 mRNAs." (PMID 36985262, 2023). "Studies of innate activation unrelated to COVID-19 are also very limited, revealing TLR1, TLR2, TLR3, TLR4, TLR7 and TLR8 activation." (PMID 36769320, 2023). "As would be expected from the SARS-CoV-2 viral activation pattern just described, TLR3, TLR7, TLR8, TLR9, NLRP3, RIG-1 and MDA-5 are activated in patients with severe COVID-19." (PMID 36769320, 2023). "Parallel to the expression of MyD88, the expression of TLR1, TLR2, TLR4, TLR5, TLR8 and TLR9 was significantly elevated in patients with severe and critical COVID-19." (PMID 35682644, 2022). "It was seen that the transcript levels of TLR3, TLR7, TLR8, and TLR9 were overexpressed in the COVID-19 patients with clinical symptoms needing hospitalization as well as in those with clinical symptoms without needing for hospitalization compared to controls." (PMID 35538443, 2022). "There was a significant upregulation of mRNA of TLR3 (fold change = 2.1, P = 0.022), TLR7 (fold change = 1.9, P = 0.025), TLR8 (fold change = 2.0, P = 0.039), and TLR9 (fold change = 2.9, P = 0.024) in COVID-19-Group B compared with the Control-Group I." (PMID 35538443, 2022).
COVID-19 (continued). "Incubation with the TLR7/TLR8 agonist induces the production of TNF-α and IL-6 in cells from HDs and COVID-19 patients." (PMID 36248842, 2022). "Together, these data suggest an association of MyD88 and a panel of TLRs (i.e., TLR1, TLR2, TLR4, TLR5, TLR8, and TLR9) with disease progression in patients with COVID-19." (PMID 35682644, 2022). "There was a significant upregulation of mRNA of TLR3 (fold change = 2.4, P = 0.017), TLR7 (fold change = 2.0, P = 0.009), TLR8 (fold change = 2.2, P = 0.004), and TLR9 (fold change = 2.9, P = 0.010) in COVID-19-Group B compared with the Control-Group III." (PMID 35538443, 2022). "A significant positive correlation was observed between CRP and mRNA expression of TLR3 (rho = 0.85, P = 0.001), TLR7 (rho = 0.80, P = 0.004), TLR8 (rho = 0.78, P = 0.010), and TLR9 (rho = 0.48, P = 0.035) in the all COVID-19 cases." (PMID 35538443, 2022). "There was positive significant correlation between ESR and mRNA expression of TLR3 (rho = 0.71, P = 0.005), TLR7 (rho = 0.62, P = 0.011), TLR8 (rho = 0.65, P = 0.029), and TLR9 (rho = 0.40, P = 0.044) in all COVID-19 cases." (PMID 35538443, 2022). "More specifically, TLR3, TLR7, TLR8, and TLR9 were upregulated in the COVID-19 cases with clinical symptoms and needing hospitalization as well as in those with clinical symptoms but without requirement for hospitalization for supportive cares." (PMID 35538443, 2022). "The mRNA expression of TLR3 (fold change = 3.4, P = 0.032), TLR7 (fold change = 2.0, P = 0.041), TLR8 (fold change = 2.8, P = 0.019), and TLR9 (fold change = 2.1, P = 0.016) was significantly upregulated in COVID-19- Group A compared with the Control-Group I." (PMID 35538443, 2022). "There was a significant upregulation of mRNA of TLR3 (fold change = 2.9, P = 0.011), TLR7 (fold change = 2.2, P = 0.020), TLR8 (fold change = 2.9, P = 0.040), and TLR9 (fold change = 2.5, P = 0.001) in COVID-19-Group A in comparison to the Control-Group II." (PMID 35538443, 2022). "There was positive significant correlation between Neutrophil–lymphocyte ratio and mRNA expression of TLR3 (rho = 0.62, P = 0.012), TLR7 (rho = 0.60, P = 0.013), TLR8 (rho = 0.49, P = 0.011), and TLR9 (rho = 0.39, P = 0.036) in all COVID-19 cases." (PMID 35538443, 2022). "In conclusion, our investigation indicated that the mRNA expressions of TLR3, TLR7, TLR8, and TLR9 are upregulated in the nasopharyngeal epithelial cells from COVID-19 patients." (PMID 35538443, 2022). "Asymptomatic COVID-19 cases displayed upregulation of ISGs and humoral response genes with downregulation of ICAM3 and TLR8." (PMID 34824360, 2021). "This study aimed to identify whether TNF and IFN-γ levels play a central role in regulating the activated state of immune cells in COVID-19 patients and explore potential links with TLR7 and TLR8 signaling." (PMID 39940907, 2025). "TLR8 activated by aPLs induces an increment in type I IFNs in antiphospholipid syndrome (APS), and this mechanism can participate in the aberrant type I IFN signaling and thrombo-inflammation present in severe COVID-19 patients." (PMID 39062904, 2024). "Compared to TLR7 and TLR9, a dramatically elevated level of TLR8 was shown in neutrophils after treatment with COVID-19 patient–derived EVs (MFI, 92.97 ± 25.07 versus 24.48 ± 5.03, P < 0.005), and this effect was suppressed in the presence of the TLR8 specific inhibitor Cu-CPT9a." (PMID 37904132, 2023). "It was observed that oxygen saturation, WBC count, Neutrophil–lymphocyte ratio, LDH level, CRP level, and ESR level had a significant positive correlation with the transcript levels of TLR3, TLR7, TLR8, and TLR9 in the COVID-19 Group A as well as COVID-19 Group B patients." (PMID 35538443, 2022). "The expression of TLR8 in CD8+ T cells was not significantly different between COVID-19 and non-COVID-19 plasma exosome treatments." (PMID 36526691, 2022).
COVID-19 (continued). "Modulation of TLR3, TLR7, TLR8, TLR9 in the epithelial cells of COVID-19 cases may estimate the disease severity and requirement for hospitalization." (PMID 35538443, 2022). "It was seen that mRNA expression of TLR3 (fold change = 2.2, P = 0.004), TLR7 (fold change = 2.5, P = 0.038), TLR8 (fold change = 3.1, P = 0.018), and TLR9 (fold change = 3.0, P = 0.026) was significantly upregulated in the COVID-19- Group A in comparison to Control-Group III." (PMID 35538443, 2022). "In addition, a significant positive correlation was detected between WBC count and transcript levels of TLR3 (rho = 0.55, P = 0.020), TLR7 (rho = 0.59, P = 0.029), TLR8 (rho = 0.44, P = 0.012), and TLR9 (rho = 0.41, P = 0.034) in the whole COVID-19 cases." (PMID 35538443, 2022). "Here in the current investigation, we attempted to measure the mRNA expression levels of TLR3, TLR7, TLR8, and TLR9 in the nasopharyngeal epithelial cells from COVID-19 patients in order to determine the role of these innate immune system molecules in the inflammatory settings of COVID-19 patients." (PMID 35538443, 2022). "Therefore, the analysis of the genotypes of TLR2, TLR3, TLR4, TLR6, TLR7, TLR8, and TLR9 is important for the study of COVID-19." (PMID 35327350, 2022). "It was observed that mRNA expression of TLR3 (fold change = 2.3, P = 0.016), TLR7 (fold change = 2.1, P = 0.033), TLR8 (fold change = 2.3, P = 0.022), and TLR9 (fold change = 2.4, P = 0.019) was significantly upregulated in the COVID-19- Group B versus Control-Group II." (PMID 35538443, 2022). "There was a significant positive correlation between percentage of oxygen saturation and transcript levels of TLR3 (rho = 0.37, P = 0.041), TLR7 (rho = 0.30, P = 0.026), TLR8 (rho = 0.35, P = 0.022), and TLR9 (rho = 0.39, P = 0.028) in the overall COVID-19 cases." (PMID 35538443, 2022). "Based on observations made relating to SARS-CoV-1, hyperinflammatory responses to COVID-19 may also be owing to TLR7 and TLR8 activity." (PMID 33498725, 2021). "The COVID-19 patient–derived EVs-induced NETs formation was suppressed completely in the presence of the vacuolar type H+-ATPase inhibitor bafilomycin A1 (BafA1, 100 nM), suggesting that endolysosomal TLRs such as TLR3, TLR7, TLR8 and TLR9 mediate NETs formation." (PMID 37904132, 2023). "In addition, the expression of TLR1, TLR4, TLR5, and TLR8 was significantly elevated in patients with severe or critical COVID-19, and the expression of TLR7 was increased in patients with moderate or critical COVID-19." (PMID 37310504, 2023). "In addition, COVID-19 plasma exosomes stimulated expression of TLR3, TLR7, TLR8, and TLR9 by PBMC." (PMID 36526691, 2022). "In order to investigate whether lower availability of ADO could contribute to the pro-inflammatory profile of COVID-19, MNCs from patients with severe COVID-19 and HDs were cultured with a TLR7/TLR8 agonist (CL097, imidazoquinoline-derived compound) under the presence or absence of ADO." (PMID 36248842, 2022). "It is tempting to speculate that the variety of chemokines produced by moDC in response to TLR8 stimulation could partially explain the infiltration of inflammatory cells into the lungs of mice treated with SARS-CoV-1 GU-rich ssRNA and even mice models of COVID-19." (PMID 33498725, 2021). "There was no significant upregulation of TLR3, TLR7, TLR8, and TLR9 in the epithelial cells from COVID-19-Group C compared to Control-Group I, Control-Group II, and Control-Group III." (PMID 35538443, 2022). "In the current investigation, we determined the expression levels of TLR3, TLR7, TLR8, and TLR9 in the epithelial cells obtained from confirmed COVID-19 cases with and without different clinical symptoms." (PMID 35538443, 2022). "Several studies have suggested the role of TLRs in enhancing humoral responses during COVID-19 infection, but so far, no study has examined the expression of TLR3, TLR7, TLR8 and TLR9 on respiratory epithelial cells from COVID-19 patients." (PMID 35538443, 2022).
COVID-19 (continued). "MicroBeads selected CD4+ T cells, CD8+ T cells, and CD14+ monocytes from PBMCs were treated with plasma exosomes from early-stage COVID-19 patients and non-COVID donors for 16 h at 37 °C, followed by flow cytometry for expression of TLR3, TLR7, TLR8, and TLR9 gating on live cells." (PMID 36526691, 2022). "TLR1, TLR4, TLR5, TLR8, and TLR9 expression levels were also significantly elevated in severe and critical COVID-19 patients; however, TLR3 expression was not correlated with the development of COVID-19, and an increased expression of TLR7 was observed only in patients with moderate COVID-19." (PMID 34835108, 2021).
lupus (39 papers, 2012 to 2026). "For example, the Y264H mutation in TLR7 causes early-onset lupus, while TLR8 gain-of-function mutations result in recurrent infections, neutropenia, antibody deficiency, and BM failure, conditions not typical of SLE." (PMID 40910948, 2026). "TLR8 deficiency in mice results in lupus-like conditions, presumably mediated by the increased TLR7 expression." (PMID 39143032, 2024). "We report here a new model of acquired fatal anemia in lupus-prone mice caused by the presence of functional human TLR8." (PMID 37495396, 2023). "Taken together, the combination of TLR7/TLR8 activation and lupus susceptibility genes expressed in TC mice functionally breached the gut barrier and decreased the expression of tight junction proteins." (PMID 37483626, 2023). "It is well documented that variants on the TLR-8 genes were associated with autoimmune and infectious diseases like systemic lupus erythematosus, type 2 diabetes, and tuberculosis." (PMID 36262248, 2022). "Here we report that TLR7 signaling drives the development of SS since TLR8-deficient (TLR8ko) mice that develop lupus due to increased TLR7 signaling by dendritic cells, also develop an age-dependent secondary pathology similar to associated SS." (PMID 34108972, 2021). "Since TLR8-deficiency in mice spontaneously leads to lupus that is accompanied by splenomegaly and altered splenic immune cell populations, we next evaluated these parameters in the context of HFD." (PMID 31552019, 2019). "Intriguing findings have been obtained from TLR8 deficient lupus-prone Nba2.Yaa mice, in which accelerated lupus nephritis and splenomegaly is observed, together with enhanced response to TLR7 ligation." (PMID 26068236, 2015). "In this context we have shown previously that TLR8-deficiency in C57BL/6 mice leads to lupus development due to increased TLR7 expression and signaling by DCs, and that this phenotype can be exacerbated under high fat diet conditions due to the additional increase of TLR7 signaling." (PMID 34108972, 2021). "Indeed, TLR8-deficiency in mice on the C57BL/6 background leads to lupus development due to increased TLR7 expression and signaling by DCs." (PMID 31552019, 2019). "Notably, high fat diet exacerbates lupus phenotypes in TLR8-deficient lupus-prone mice." (PMID 35795671, 2022). "TLR7 and TLR8 are encoded by X-linked genes, which may render females more susceptible to lupus." (PMID 26068236, 2015). "Because TLR7 expression and DC signalling are enhanced in TLR8‐deficient animals on the C57BL/6 background, lupus develops." (PMID 40976999, 2025). "The pathogenesis of systemic lupus erythematosus (SLE) is linked to the differential roles of toll-like receptors (TLRs), particularly TLR7, TLR8, and TLR9." (PMID 38791389, 2024). "A second study examined the effects of Tlr7 ablation in Tlr8−/− female mice that develop both lupus and SD-related autoimmunity contemporaneously." (PMID 39310226, 2024). "Our results prove a critical role for miR-574-5p-mediated TLR8 activity in lupus pathogenesis or progression." (PMID 38589923, 2024). "Previous reports have shown that VitD3 reduces TLR7 mRNA expression in PBMCs from patients with systemic lupus erythematosus and also reduces TLR8 mRNA expression in monocytes." (PMID 38839691, 2024). "As for a D34A mutation causing murine lupus, we recorded a gain of TLR7 and, to a lesser extent, TLR8 activity with the I317M (in vitro) and G325C (in vitro and ex vivo) variants in the context of SLE." (PMID 38869500, 2024). "Human TLR8 induces an inflammatory phenotype in BM erythroblastic island central macrophages of lupus-prone Sle1.Yaa mice." (PMID 37495396, 2023). "Studies in TLR8−/− animals revealed that these mice develop lupus and SD concomitantly, as sialadenitis, autoantibody production, glomerulonephritis, and lung inflammation were observed." (PMID 39916928, 2023).